ALB (albumin)
Diseases named in the same sentence as ALB in open-access papers (continued):
Sharing a sentence is not in itself a finding about the gene and the disease.
Sepsis (continued). "The purpose of this study was to explore the relationship between blood urea nitrogen to serum albumin ratio and 28-day in-hospital mortality in patients with chronic heart failure complicated by sepsis admitted to the intensive care unit (ICU)." (PMID 40104144, 2025). "Building on the findings from the SAFE trial, the Albumin Italian Outcome Sepsis (ALBIOS) trial further investigated the role of albumin in patients with sepsis or septic shock." (PMID 40699702, 2025). "In this prospective cohort study of patients with sepsis, serum albumin and the SIC score emerged as independent and complementary predictors of the clinical severity, 30-day mortality, and bleeding risk." (PMID 40648856, 2025). "The Surviving Sepsis Guidelines recommend intravenous (IV) crystalloid solutions as the first fluid choice, while albumin can be considered in patients requiring large fluid volumes." (PMID 40386509, 2025). "During the onset of sepsis, the inflammatory response of the body leads to a significant decrease in albumin levels, which is considered one of the manifestations of the inflammatory state that septic patients are in." (PMID 40104144, 2025). "While serum albumin has long been recognized as a reliable prognostic biomarker in sepsis, its interpretation is often limited by confounding effects of hemodilution, fluid overload, and redistribution." (PMID 40806877, 2025). "Sepsis, use of human albumin, age, mechanical ventilation, aminoglycoside administration, and serum creatinine levels were identified as predictive factors for AKI in patients with AHF." (PMID 40124680, 2025). "Serum Lac, PLT, TBA, BUN, D-dimer, TNF-α levels of the early stage of sepsis, pH, Glu, ALB, TBA, CK-MB, PCT, and TNF-α levels of the serious stage of sepsis and complications with statistically significant differences were verified by the ROC curve." (PMID 39266629, 2025). "Elevated LDH (median 325 mg/dL) and decreased albumin levels (median 26 g/L) can be used as early indicators of sepsis." (PMID 40722642, 2025). "Albumin infusion has been considered a potential treatment option for sepsis, septic shock, and fluid resuscitation in critically ill patients admitted to the intensive care unit (ICU) for several decades." (PMID 40699702, 2025). "We also found a 1.6 increase in the odds of death in sepsis patients with a 14-day maximum ALB level below the cutoff and a 1.8 increase in the odds of death with the ALB level on day 7 below the cutoff." (PMID 40438354, 2025). "Serum albumin and serum creatinine are routine clinical biochemical markers and play important roles in assessing disease severity and prognosis in sepsis patients." (PMID 40978746, 2025). "In the SIRS/sepsis cohort plasma LBP negatively correlated with albumin (r = −0.254, p = 0.002) and positively with bilirubin (r = 0.268, p = 0.001)." (PMID 39997462, 2025). "It showed that patients with higher levels of PCT or PT were much more likely to develop sepsis than those with lower levels, while patients with higher levels of albumin were less likely to develop sepsis." (PMID 39975676, 2025). "The lactate-to-albumin ratio (LAR) can be considered an indicator of the heightened inflammatory response in sepsis." (PMID 40046181, 2025). "Future research should further refine the optimal strategy for albumin administration in sepsis resuscitation, considering factors such as timing, dosage, and patient-specific conditions to develop a safer, more personalized treatment approach." (PMID 40841985, 2025). "Fibrinogen and albumin data were unavailable for approximately two-thirds of sepsis patients meeting the inclusion criteria." (PMID 40607037, 2025). "Our study found that among ischemic stroke patients with sepsis, those who received combined crystalloid and albumin therapy had a higher 90-day mortality rate and experienced longer ICU and hospital lengths of stay." (PMID 41468394, 2025).
Sepsis (continued). "In the context of critically ill patients with chronic heart failure complicated by sepsis, there exists a significant correlation between blood urea nitrogen to serum albumin ratio (BAR) and 28-day mortality." (PMID 40104144, 2025). "The adjunctive use of albumin with loop diuretics, as seen in our case, has been described in sepsis-related and idiopathic CLS, although its utility in ICI-induced CLS remains anecdotal and warrants systematic evaluation." (PMID 41281016, 2025). "More significantly, the earlier the ALB level is raised to a certain level, the higher the 28-day survival rate of patients with sepsis." (PMID 40438354, 2025). "As per Delong test, while comparing AUC,LAR was statistically significant over SOFA score (p value < 0.05) and albumin alone (p value < 0.05) to predict mortality in sepsis." (PMID 40130722, 2025). "The ultimate multivariable logistic model revealed five predictors (sepsis, use of human albumin, mechanical ventilation, use of aminoglycosides, and Scr levels measured in μmol/L)." (PMID 40124680, 2025). "The BAR (blood urea nitrogen-to-serum albumin ratio) combines markers of kidney function and protein status, representing a potentially more accurate predictor of outcomes in sepsis." (PMID 41228403, 2025). "Prior research has established the BUN to ALB ratio (BAR) as a significant forecast index in sepsis, post-cardiac surgery, severe COVID-19,and acute exacerbation of chronic obstructive pulmonary disease (AECOPD)." (PMID 40373080, 2025). "Our findings also suggested that male patients with bacterial infections and high PCT levels, lower albumin levels, or prolonged PT were more likely to develop sepsis." (PMID 39975676, 2025). "Neutrophils mirror acute responses, lymphocytes underscore longer-term adaptive capabilities, and serum albumin highlights nutritional sufficiency, forming a composite tool that traverses the acute-chronic spectrum of sepsis impacts." (PMID 40766844, 2025). "The selected biomarkers here—neutrophils, lymphocytes, and albumin—represent critical nodes within the inflammatory-nutritional network intricately involved in sepsis pathophysiology." (PMID 40766844, 2025). "In the early stages of sepsis, fibrinogen levels rise, exacerbating inflammation, while albumin levels typically decrease, reflecting the complex interplay of inflammation." (PMID 40134983, 2025). "The table shows that there is a significant correlation between albumin level changes and the probability of sepsis." (PMID 40773463, 2025). "Dogs with nSIRS and sepsis had significantly lower concentrations of plasma albumin compared to healthy dogs on D1." (PMID 40607352, 2025). "Beyond static measurements, recent research underscores the importance of dynamic trends in albumin levels during early sepsis resuscitation." (PMID 40806877, 2025). "In female SIRS/sepsis patients, the correlation with albumin was significant (r = −0.369, p = 0.017)." (PMID 39997462, 2025). "This study investigated the prognostic value of the creatinine to albumin ratio in patients with sepsis complicated by acute kidney injury." (PMID 41425961, 2025). "The current findings are corroborated by emerging evidence regarding the pathophysiology of albumin kinetics, particularly in the context of capillary leak and altered fluid distribution in sepsis." (PMID 40806877, 2025). "Among sepsis patients, higher SOFA scores, LAR, and Lactate values, along with lower albumin levels, were associated with poor in-hospital outcomes, including a greater need for inotropes and mechanical ventilation." (PMID 40130722, 2025). "Early albumin use in patients with cirrhosis and sepsis has been evaluated in two studies, which demonstrated that using albumin for initial fluid resuscitation led to higher hypotension reversal at 3 h compared to crystalloids alone." (PMID 40386509, 2025). "The Saline versus Albumin Fluid Evaluation (SAFE) study analyzed 1218 patients with severe sepsis from an initial dataset." (PMID 40649163, 2025).
Sepsis (continued). "The aim of our study was to compare the procalcitonin-to-albumin ratio (PAR) and C-reactive protein(CRP)-to-albumin ratio (CAR) in predicting sepsis and its severity in children and to know which one is better." (PMID 40351994, 2025). "Serum albumin, as a key marker of nutritional status, is inversely related to the severity of sepsis in patients." (PMID 40438347, 2025). "Our results extended the application of the albumin infusion to the realm of sepsis, indicating its potential value for clinicians managing patients with AP admitted to the ICU." (PMID 40773463, 2025). "We plotted the ROC curves for LAR, lactate, and albumin to evaluate their predictive value for short-term and long-term all-cause mortality in patients with CHF and sepsis." (PMID 40735448, 2025). "The study will assess the clinical effects of early albumin administration in sepsis patients, providing evidence-based insights to optimize treatment strategies." (PMID 40841985, 2025). "Further prospective controlled studies are needed to clarify the causal relationship between the reduction of inflammatory markers and ALB infusion to guide the prevention and treatment of sepsis better." (PMID 40438354, 2025). "The utilization of albumin in the management of sepsis remains a subject of controversy, with clinical outcomes exhibiting a high degree of variability due to individual patient factors." (PMID 40841985, 2025). "Although numerous randomized controlled trials have explored the role of albumin administration in patients with sepsis or septic shock, its clinical benefits remain uncertain." (PMID 40649163, 2025). "27.85 g/L would work as the target level of ALB infusion on 7 day to improve the prognosis of sepsis patients." (PMID 40438354, 2025). "This study investigates the association between red cell distribution width to albumin ratio (RAR) and clinical outcomes in elderly sepsis patients." (PMID 40964688, 2025). "When contextualized within existing research, the present findings align with some prior conclusions while also offering new insights into the relationship between albumin use and renal outcomes in sepsis patients." (PMID 40841985, 2025). "Previous research indicate that concentration of BUN and ALB can be affected by renal function, sepsis, age, etc, which are more prominent in elderly patients." (PMID 40373080, 2025). "These mixed results have fueled ongoing debates about the role of albumin in fluid resuscitation for sepsis and septic shock." (PMID 40699702, 2025). "The complementary roles of different biomarkers, especially the synergistic effect of presepsin with albumin, support a combined approach to sepsis diagnosis." (PMID 40868016, 2025). "This study confirms NLPR as a robust prognostic biomarker for sepsis, showing strong associations with key inflammatory and coagulation markers, including CRP, lactate, and D-dimer, as well as decreased albumin and lymphocyte counts." (PMID 40242435, 2025). "The final results showed that pH (OR = 0.003, 95% CI = 0.000–0.121, P = 0.002), ALB (OR = 0.923, 95% CI = 0.862–0.988, P = 0.021), and CK-MB (OR = 0.996, 95% CI = 0.992–0.999) were protective factors for the prognosis of sepsis." (PMID 39266629, 2025). "The CRP-to-albumin ratio combines nutritional and inflammatory status and has been extensively examined as an independent prognostic marker in sepsis, infections, malignancies, and other diseases." (PMID 41010574, 2025). "The calculation of IAM reflects the interaction between plasma albumin concentration and PV, which vary during sepsis management." (PMID 40806877, 2025). "Lower serum albumin levels and higher C-reactive protein (CRP) concentrations were independently associated with sepsis (OR = 0.24, 95% CI 0.09–0.62, p = 0.003; OR = 1.013, 95% CI 1.001–1.024, p = 0.027, respectively)." (PMID 41597022, 2025).
Sepsis (continued). "The ROC curve analysis shows that LAR has a better predictive value for the prognosis of patients with CHF and sepsis compared to lactate and albumin." (PMID 40735448, 2025). "In patients with sepsis, plasma and albumin have also been found to have a potential protective effect on the endothelium through antioxidant and anti-inflammatory effects." (PMID 39944316, 2025). "ALP to albumin ratio (APAR) was an easily accessible indicator for adverse outcomes in patients with sepsis, cancer, and coronary artery disease." (PMID 41245592, 2025). "As per Delong test, while comparing AUC, LAR was statistically significant over SOFA score (p value < 0.05) and albumin alone (p value < 0.05) to predict need of mechanical ventilation among sepsis cases." (PMID 40130722, 2025). "Reflecting this mixed evidence, the latest SSC sepsis guidelines offer a weak recommendation for albumin supplementation in patients requiring large-volume crystalloid resuscitation." (PMID 41468394, 2025). "In our study, it was determined that low 0, 24, and 48 h albumin values, a high 24th hour lactate value, and a decrease in the 24 h LC in sepsis patients increased hospital mortality." (PMID 40868186, 2025). "Emulated trial: Effect of albumin in combination with crystalloids compared tocrystalloids alone on 28-day mortality in patients with sepsis." (PMID 39899627, 2025). "The reduction of albumin is commonly seen in both acute and chronic inflammatory processes, such as sepsis, liver disease, and kidney disease, and is closely related to the severity of the disease, length of hospitalization, and ultimate prognosis." (PMID 40735448, 2025). "Fibrinogen and albumin tests are bound to coagulation and liver function tests, respectively, and are routinely examined in Chinese hospitals for patients with sepsis in the ED." (PMID 40607037, 2025). "Albumin is closely related to sepsis, and albumin plays an important role in the onset, progression, and prognosis of sepsis." (PMID 40104144, 2025). "According to Sreeraj, in patients with sepsis, the ratio of INR to albumin represents an independent risk factor for mortality and can be employed for the early evaluation of disease severity and progression." (PMID 40703270, 2025). "IV infusion over 30 min; single dose of BAY 1351 15 or 3 mg/kg within 16 h of sepsis onset or placebo (human albumin)." (PMID 41009426, 2025). "Despite the lack of clinical benefit from albumin therapy in stroke patients, emerging data support the use of crystalloid and albumin combination therapy for improving outcomes in sepsis." (PMID 41468394, 2025). "The use of combined crystalloid and albumin for fluid resuscitation in sepsis remains highly controversial." (PMID 41468394, 2025). "Replacement therapy is generally recommended when albumin levels fall below 2 g/dL in patients with sepsis or major chronic illnesses." (PMID 41303773, 2025). "The SHAP method identified procalcitonin, albumin, prothrombin time, and sex as the important variables contributing to the prediction of sepsis." (PMID 39975676, 2025). "Prior studies have shown that serum albumin is an autonomous predictor of mortality in elderly patients with sepsis." (PMID 40680007, 2025). "This TTE study examined the impact of albumin use on the development of SA-AKI in sepsis patients, adhering to the research design principles of a randomized trial to estimate causal effects from observational data." (PMID 40841985, 2025). "These diverse features of ALB render it an essential role in critically ill patients, especially those with sepsis." (PMID 40438354, 2025). "High levels of homocysteine are described in elderly, whereas lower Hcy levels were shown in sepsis patients of the same aged cohort, correlating with high neutrophil numbers and decreased serum albumin." (PMID 40413366, 2025).
Sepsis (continued). "It is therefore recommended that future research extend follow-up durations to evaluate the sustained impact of albumin therapy on kidney function and overall prognosis in sepsis patients." (PMID 40841985, 2025). "Recent research studies have discovered that the albumin level is strongly related to the adverse outcomes of sepsis patients." (PMID 40538408, 2025). "In sepsis, decreased serum albumin level is observed due to factors such as inflammation, oxidative stress, and endothelial injury." (PMID 40978746, 2025). "Our analysis revealed a statistically significant association between Albumin Corrected Anion Gap (ACAG) and 28-day in-ICU mortality among sepsis patients with chronic heart failure." (PMID 41401154, 2025). "First, the SIC score and serum albumin levels exhibit a correlated pattern in patients with sepsis; when one parameter is altered, the other tends to be altered as well." (PMID 40648856, 2025). "Our systematic analysis establishes NT-proBNP, lactate, albumin, oxygenation index, and MAP as independent mortality risk determinants in sepsis patients." (PMID 40470352, 2025). "Alkaline phosphatase to albumin ratio (APAR) is an emerging prognostic indicator for sepsis, cancer, and coronary artery disease." (PMID 41245592, 2025). "This study provides new data on albumin kinetics in a very sick cohort with sepsis, describing the net effects of capillary leakage counterbalanced by lymphatic return." (PMID 40057738, 2025). "They concluded that APACHE II is better than the CRP/Albumin ratio in predicting post-operative complications and mortality in sepsis patients." (PMID 40091950, 2025). "Several research studies already revealed that albumin can forecast poor outcomes among patients with sepsis or AKI." (PMID 40538408, 2025). "In contrast, Group 3 comprised more female patients and presented with the best kidney function, the lowest albumin levels, the most sepsis cases, longer hospital stays, more ICU admissions and a higher frequency of receiving interventions." (PMID 40583865, 2025). "In the early phase of sepsis, the administration of 1,000 mL of Ringer lactate (n=29) or 400 mL of 4% albumin (n=31) increased the sublingual proportion of perfused vessels and the perfused vascular density, but this effect was lost in later stages." (PMID 41247634, 2025). "Meanwhile, low albumin levels and high SAPS 3 scores were associated with in-hospital mortality in patients with sepsis." (PMID 41343415, 2025). "Despite these insights, most studies examining albumin in sepsis have concentrated on intensive care settings or evaluated serum concentrations rather than actual mass-based measures." (PMID 40806877, 2025). "Neurotoxicity was found to be associated with lower birthweight and gestational age, the presence of cerebral injury, decreased serum albumin concentration, prolonged acidosis, hypothermia, and sepsis." (PMID 41153845, 2025). "CRP/Albumin ratio>2 presented the highest sensitivity and specificity in the prediction of 90-day mortality in patients with sepsis/septic shock." (PMID 40091950, 2025). "Our aim in this study is to determine the benefits of serum lactate, albumin, and BE values by excluding the factors that affect their levels in predicting prognosis and mortality in patients with sepsis when evaluated together." (PMID 40868186, 2025). "Reduced albumin levels in sepsis impair its binding capacity, increasing the toxicity of endotoxins and exacerbating the inflammatory response, which can cause more severe damage and increase the risk of death." (PMID 40470352, 2025). "To illustrate and compare biases, we investigate the impact of albumin on sepsis mortality using data from a publicly available intensive care database, MIMIC-IV (section Application: evidence from MIMIC-IV on which resuscitation fluid to use)." (PMID 39899627, 2025).